PTX4 (pentraxin 4)
Synonyms: C16orf38
Tractability: Antibody: UniProt places it where antibodies can reach, with high confidence; UniProt predicts a signal peptide or a membrane-spanning region; its Gene Ontology location is reachable by antibodies, with medium confidence.
Gene: Protein-coding gene on chromosome 16 (1,485,886 to 1,488,981, reverse strand). Ensembl gene ENSG00000251692.
Subcellular location: Secreted
Gene Ontology:
Cellular component: extracellular region
Genetic constraint (gnomAD): Loss-of-function variants: 18 observed, 16.15 expected, observed/expected ratio (o/e) 1.11, 90% interval 0.77 to 1.64. The upper end of that interval is the gene's LOEUF score, 1.64, which puts it in group 6 of 6, group 1 being the genes least tolerant of losing a copy. Missense variants: 628 observed, 563.56 expected, observed/expected ratio (o/e) 1.11, 90% interval 1.04 to 1.19. Synonymous variants: 297 observed, 261.06 expected, observed/expected ratio (o/e) 1.14, 90% interval 1.03 to 1.25.
Homologues: Orthologues: chimpanzee PTX4 (97% identical), macaque PTX4 (90% identical), dog PTX4 (71% identical), guinea pig PTX4 (67% identical), mouse Ptx4 (65% identical), rat Ptx4 (64% identical), rabbit PTX4 (63% identical), pig PTX4 (60% identical), tropical clawed frog ptx4 (46% identical), zebrafish zmp:0000000984 (6% identical). Paralogues in human: NPTX2 (24% identical), NPTX1 (22% identical), PTX3 (17% identical), APCS (12% identical), CRP (12% identical).
Diseases named in the same sentence as PTX4 in open-access papers:
PTX4 is named in the same sentence as 5 diseases in open-access papers, as found by Europe PMC text mining. Sharing a sentence is not in itself a finding about the gene and the disease. The quoted sentences say what the papers report.
cancer (2 papers, 2022 to 2024). A tumor composed of atypical neoplastic, often pleomorphic cells that invade other tissues. "Additionally, PTX3 surpasses other members of the pentraxin family, such as NP1, NP2, and PTX4, in terms of its prognostic significance across a broad range of cancers." (PMID 39594709, 2024).
tumor (2 papers, 2017 to 2020). "SAP and PTX4 share highly structural homology with CRP, but limited research has focused on their association with the tumor, similarly with the neuronal pentraxins." (PMID 33013829, 2020). "This indicates that PTX4 might be playing specific roles in innate immunity or tumor progression." (PMID 33013829, 2020).
PTX4 also shares sentences with these, for which no sentence is quoted: infection (1 paper); ischemic stroke (1); osteopetrosis (1).